SPARC (secreted protein acidic and cysteine rich)
Diseases named in the same sentence as SPARC in open-access papers (continued):
Sharing a sentence is not in itself a finding about the gene and the disease.
neuroblastoma (continued). "To investigate the effects of stroma-derived SPARC on neuroblastoma tumorigenesis, we developed an in vivo model that mimicked Schwannian-rich neuroblastoma by mixing highly tumorigenic KCNR cells (neuroblastic or N-type cells) cells with non-tumorigenic SHEP cells." (PMID 27776337, 2016). "Further, we found that FA are toxic to neuroblastoma cells in hypoxic conditions, suggesting that SPARC may induce lipotoxicity in neuroblastoma tumors." (PMID 27776337, 2016). "The in vivo results thus corroborate the in vitro findings and support the hypothesis that ER stress plays a key role in regulating the induction of apoptosis in SPARC-overexpressed neuroblastoma cells." (PMID 23123816, 2013). "Based on the in vitro results, it could be proposed that SPARC overexpression invokes ER stress, which in turn enhances autophagy-mediated apoptosis in neuroblastoma." (PMID 23123816, 2013). "Given the complexity of events initiated as part of ER stress induction, it could be proposed that there is an interplay of multiple intracellular pathways during SPARC-induced autophagy and apoptosis in neuroblastoma cells." (PMID 23123816, 2013). "In neuroblastoma xenografts, SPARC peptides inhibited angiogenesis and tumour growth in vivo." (PMID 22957090, 2012). "The overexpression of SPARC blocks angiogenesis both in vitro and in vivo in neuroblastoma." (PMID 22481923, 2012). "The potent anti-tumor activity of SPARC peptide FSEC in a preclinical model of neuroblastoma indicates that it may be an effective treatment for children with high-risk neuroblastoma, as well as other malignancies." (PMID 20525313, 2010). "Our laboratory has previously shown that full-length Secreted Protein Acidic and Rich in Cysteine (SPARC) and a SPARC peptide corresponding to the follistatin domain of the protein (FS-E) potently block angiogenesis and inhibit the growth of neuroblastoma tumors in preclinical models." (PMID 20525313, 2010). "Further, flow cytometric analysis showed that SPARC transfection alone or in combination with radiation (IR) dosage of 8 Gy resulted in a significant increase of the sub-G0/G1 population of cells, which indicates the induction of apoptosis in the SK-N-AS and NB-1691 neuroblastoma cells." (PMID 23123816, 2013). "SPARC (secreted protein and rich in cysteine), a matricellular protein found to be underexpressed in certain cancers, has emerged as a multifunctional protein capable of inhibiting the growth of neuroblastomas, leukemia, pancreatic, colorectal and ovarian cancers." (PMID 22069448, 2011). "SPARC overexpression alone or in combination with radiation treatment has been shown to enhance cleavage of caspase 3 and PARP in neuroblastoma cells." (PMID 23123816, 2013). "We have previously shown that full-length SPARC and SPARC peptide FS-E, that corresponds to the highly conserved EGF-like module of the follistatin domain, potently inhibit angiogenesis and neuroblastoma tumor growth in preclinical models." (PMID 20525313, 2010). "Our results demonstrate that SPARC peptide FSEC has potent anti-angiogenic and anti-tumorigenic effects in neuroblastoma." (PMID 20525313, 2010). "Here, we developed a novel in vivo model of stroma-rich neuroblastoma using non-tumorigenic SHEP cells with modulated levels of SPARC, mixed with tumorigenic KCNR cells." (PMID 27776337, 2016). "In a parallel to our observations, overexpression of the matricellular protein SPARC (secreted protein acidic and rich in cysteine) inhibits growth and migration of MDA-MB-231 cells, and yields elevated PTEN and growth suppression in neuroblastoma cells." (PMID 23648148, 2013). "They showed that MVD value of SPARC-treating group was significantly lower than non-treated control group and demonstrated that purified SPARC potently inhibited neuroblastoma growth and angiogenesis in vivo." (PMID 20565704, 2010). "Similarly, in breast and prostate cancers and neuroblastoma, the majority of neoplastic cells do not express SPARC." (PMID 20525313, 2010).
neuroblastoma (continued). "Substrate adherent, non-tumorigenic (S-type) neuroblastoma SHEP cells share many characteristics with Schwann cells, including tyrosinase activity specific for melanocytes and expression of fibronectin, vimentin, collagen IV, and SPARC." (PMID 27776337, 2016).
colon carcinoma (30 papers, 2004 to 2024). "SPARC is secreted into the bloodstream in response to exercise, and its release was found to be associated with the inhibition of colon tumor formation via the increasing of apoptosis." (PMID 35409299, 2022). "It is believed that inhibition of SPARC expression is associated with the tumor progress and invasion process of colon cancer." (PMID 20565704, 2010). "In colon cancer patients, high SPARC mRNA expression was associated with advanced tumor stage (14,62 ± 1,13 vs. 14,24 ± 1,15; p=0,007), positive lymph node metastasis (14,64 ± 1,12 vs. 14,23 ± 1,13; p=0,003) and positive vascular invasion (14,28 ± 1,2 vs 14,51 ± 0,93, p=0,043)." (PMID 36895491, 2023). "Eight significantly over‐expression genes in tumour tissues (BGN, THBS2, SPARC, CDH11, MFAP2, MMP11, SPP1 and THY1) were defined as significantly signature genes that implicated in colon cancer metastasis progress." (PMID 36377223, 2022). "Two anti-tumor myokines, OSM and SPARC, have recently been identified that inhibit colon tumor formation and inhibit breast cancer cell growth, respectively." (PMID 35409299, 2022). "Of note, among the DEGs identified upon CD44s ectopic expression which correlate with ZEB1hi/ESRP1lo (and CMS4) colon cancers, the SPARC gene, a pEMT marker in the EpCAMhi/lo state transitions, was found." (PMID 36346211, 2022). "Some studies address the role of SPARC in activating caspase-3 and caspase-8 dependent apoptosis, which reveals a potential benefit of physical exercise in decreasing the incidence of colon cancer." (PMID 33807959, 2021). "In colon cancer, the myokine SPARC was upregulated in exercising mice and inhibited proliferation and increased apoptosis in colon cancer cells in vitro." (PMID 33806053, 2021). "SPARC is highly expressed in many tumors, and a research showed that its expression is related with metastasis and recurrence of colon cancer." (PMID 32812032, 2020). "Other group showed that direct co-culture with bone-marrow MSCs increased expression of EMT-related genes, e.g. fibronectin, SPARC, and galectin 1 in colon cancer cells (KM12SM)." (PMID 30310111, 2018). "SPARC expression was mainly in the stromal cells surrounding the colon cancer, and was significant difference in those tissues with the lymph node metastasis and differentiation degree of tumor." (PMID 20565704, 2010). "The results of the analysis of the cinicopathological parameters showed that SPARC expression influences independently overall and disease-free survival of patients with colon cancer and is an independent prognostic factor for colon cancer." (PMID 20565704, 2010). "Linear regression analysis of SPARC-positive percentage of individual cases in MSC showed significant correlation with MVD in these human colon cancer specimens (P < 0.05, r = -0.578)." (PMID 20565704, 2010). "SPARC was mainly localized in the cytoplasm and was detected in the normal colonic epithelial cells, the colon cancer cells and the mesenchymal and stromal cells (MSC) of colon cancer." (PMID 20565704, 2010). "ND + Ex revealed predominantly higher SPARC expression in colon tumors than seen in ND." (PMID 38792787, 2024). "SPARC mRNA expression was a more specific marker for colon cancer patients." (PMID 36895491, 2023). "Notably, TGF-β cooperates with PDGF to regulate CAFs differentiation and “Platelet-derived growth factor binding” was the second top-enriched molecular function in the genes correlating with SPARC in breast and colon cancers." (PMID 36604669, 2023). "Furthermore, the downregulation of SPARC was observed in 5-fluorouracil and irinotecan-resistant colon cancer cells, and its re-expression was observed to restore sensitivity." (PMID 37176114, 2023). "In a cohort of 114 patients with colon cancer, a significant negative association was observed for SPARC expression in mesenchymal and stromal cells with the differentiation of tumors." (PMID 36895491, 2023).
colon carcinoma (continued). "SPARC was also highly expressed in esophageal and liver cancer tissues and was closely related to the degree of malignancy, but its expression was low in pancreatic and colon cancer tissues." (PMID 35211625, 2022). "SPARC (secreted protein acidic and rich in cysteine) was also released from skeletal muscle upon contraction and suppressed colon tumourigenesis in exercising mice, primarily via the induction of apoptosis in colon carcinoma cells." (PMID 34359731, 2021). "They showed that SPARC induces a reduction in growth in a human colon cancer cell line in vitro and that regular injection of a low dose of SPARC into mice (to mimic the rise during acute exercise) reduced formation of colon cancer lesions." (PMID 33864493, 2021). "Finally, to begin to address the biological significance of these studies, we undertook to validate that treatment of HT-29 colon cancer cells with 5 μM 5-Aza would relieve suppression of SPARC gene expression." (PMID 23902433, 2013). "In colon cancer tissues, SPARC expression was negatively correlated with VEGF expression and MVD." (PMID 22957090, 2012). "With the results of current study, we speculate that endogenous expression of SPARC may inhibit VEGF-stimulated capacity of angiogenesis in the development process of colon cancer." (PMID 20565704, 2010). "Patients with low or absence expressing SPARC had significantly worse overall survival and disease-free survival in a Single Factor Analysis; Cox Regression Analysis, SPARC emerged as an overall survival and disease-free survival independent prognostic factor for colon cancer." (PMID 20565704, 2010). "SPARC maybe involved in the regulation of anti-angiogenesis by which it may serve as a novel target for colon cancer treatment as well as a novel distinctive marker." (PMID 20565704, 2010). "Recently, the role of SPARC expression in colon cancer was concerned greatly." (PMID 20565704, 2010). "VEGF expression was up-regulated in colon cancer along with the decreased expression of SPARC." (PMID 20565704, 2010). "Although SPARC is unique in its expression peaking at pEMT states and earmarking the transition between EpCAMlo and EpCAMhi in both cell lines and in mes-like cells from patient-derived colon cancers, it seems unlikely that specific genes exist that can independently elicit pEMT." (PMID 34036938, 2021). "Therefore, it may support an hypothesis that SPARC potentially regulates the expression of angiogenesis factor VEGF during colon cancer development, by regulating indirectly the formation of blood capillary, to impact the clinical prognosis of patients." (PMID 20565704, 2010). "The level of EVs containing SPARC (extracellular matrix) and LRG1 (cell signaling) are higher in the serum from patients with stage III colon cancer than in the serum from healthy control individuals, and they were predictive of disease recurrence." (PMID 36831450, 2023). "Apart from SPARC, the other genes correlating with immune infiltration included SPOCK1 and INHBA which were highly correlated with CAFs in colon cancer, as well as TUBB (correlations with myeloid dendritic cells in thymoma)." (PMID 36604669, 2023). "Five genes (BGN, THBS2, SPARC, CDH11 and SPP1) were initially identified as potential biomarkers and therapeutic targets of colon cancer metastasis." (PMID 36377223, 2022). "Expression of SPARC was significantly correlated with the expression of VEGF and MVD in colon cancer tissues." (PMID 20565704, 2010). "In summary, the expression of SPARC protein can emerge in tumor cells and MSC of colon cancer, but mainly in MSC." (PMID 20565704, 2010). "SPOCK2 belongs to a group of SPARC proteins, which encompasses various proteins that have been studied in various gastrointestinal malignancies, such as biliary tract cancers (BTC), PDAC, and colon cancer." (PMID 37188984, 2023). "A similar reduction in the formation of colon cancer lesions was reported with regular exercise in wild-type but not in SPARC-null mice." (PMID 33864493, 2021).
colon carcinoma (continued). "Another study showed that the downregulated or absent expression of SPARC is related to high-speed progression of human colon cancer." (PMID 31186631, 2019). "The low expression or absence of stromal SPARC was an independent prognostic factor for poor prognosis of colon cancer." (PMID 20565704, 2010). "Using Spearman rank correlation analysis, SPARC expression in MSC was negative significantly related with VEGF in colon cancer tissue (P < 0.05, r = -0.208)." (PMID 20565704, 2010). "The possible reason for the low expression or absence of SPARC in high malignant colon cancer tissue is that either endogenous SPARC expression is down-regulated or its secretion is arrested by other factors." (PMID 20565704, 2010). "Expression of SPARC protein was determined by immunohistochemistry staining in 114 cases of paraffin-embedded colon cancer tissues and their corresponding non-diseased colon tissue." (PMID 20565704, 2010). "Interestingly, that stromal expression of SPARC and SPP1 was prognostic for the reduced RFS and PFS, respectively, only in rectal cancer patients, while S100A4 correlated with poor OS rates in CRC and colon cancer patients." (PMID 36895491, 2023). "In addition, low expression or absence of SPARC protein in MSC can be considered as an important independent unfavourable prognostic factor of colon cancer." (PMID 20565704, 2010). "Our results also showed that SPARC expression was mainly in MSC and decreased in colon cancer tissue, which indicated that SPARC might inhibit the invasion and metastasis of tumor during colon cancer development." (PMID 20565704, 2010). "A significant overlap was detected with several relevant gene families, including colon cancer progression (e.g., FN1, IGBP3, PLAUR and TIMP1; P=0.00052), tumour cell apoptosis (e.g., BID, TNFRSF21, PHLDA1 and NOTCH1; P=1.46 × 10–6) and cell proliferation (e.g., CTGF, SPP1, FOLR1 and SPARC)." (PMID 21119668, 2010). "All of these results suggest that SPARC may inhibit VEGF expression during the process of new blood vessel growth by which indirectly control the development, growth, invasion and metastasis of tumor cells in colon cancer." (PMID 20565704, 2010). "The reduction in tumorigenesis and increased caspase activity which occurred following acute exercise in azoxymethane-induced colon cancer in wild-type mice was not seen in SPARC-null mice, suggesting that SPARC may be a critical myokine involved in the anticancer effects of exercise." (PMID 28481292, 2017). "This selective increase in SPARC and LRG1 in colon cancer EVs, as opposed to other cancers such as gastric, thyroid, or cervix cancers, underscores the specificity of these markers for colon cancer." (PMID 39370455, 2024).
hepatocellular carcinoma (29 papers, 2003 to 2025). A malignant tumor that arises from hepatocytes. "In NAFLD-associated hepatocellular carcinoma, the inhibition of SPARC accelerates the development of cancer and cardiovascular disease." (PMID 35721704, 2022). "In hepatocellular carcinoma, miR-29a-3p suppressed cell growth by inhibition of Secreted protein acidic and rich in cysteine (SPARC) while SPARC-deficient mice were shown to develop urothelial carcinoma much earlier than mice expressing SPARC." (PMID 29599914, 2018). "In oncology, many studies have shown that SPARC is overexpressed in different forms of cancer, including cervical carcinoma, colon cancer, and hepatocellular carcinoma." (PMID 34827687, 2021). "Further, miR-29a was found to be downregulated in hepatocellular carcinoma, and was shown to inhibit cell proliferation by downregulating SPARC." (PMID 28212562, 2017). "In hepatocellular cancer cell-line xenografts, SPARC overexpression significantly delayed tumour formation, reduced tumour size, and decreased MVD in comparison with control xenografts." (PMID 22957090, 2012). "A systemic review and meta-analysis showed prognostic value of SPARC in hepatocellular carcinoma." (PMID 37509139, 2023). "In line with other reports, miR-29a and SPARC expression levels were inversely correlated in hepatocellular carcinoma cell lines, and over-expression of miR-29a resulted in a significant reduction in SPARC mRNA and protein of hepatocellular carcinoma and the trabecular meshwork." (PMID 25786138, 2015). "Interestingly, SPARC over-expression in hepatocellular carcinoma cells results in a reduced tumorigenicity." (PMID 21818335, 2011). "In hepatocellular carcinomas, SPARC expression correlates with tumor angionenesis." (PMID 21818335, 2011). "Indeed, miR-211 (micro RNA-211) has been shown to down-regulate SPARC in hepatocellular carcinoma." (PMID 31554208, 2019). "Co-treatment with KPA also decreased the expression of genes, regulating the progression of fibrosis (e.g., COL6A3, AEBP1, SPARC, TNC, LAMB1, BGN) and hepatocellular carcinoma (e.g., COL4A1, COL4A2, TUFT1, VCAN, NID1)." (PMID 39404414, 2024). "For example, SPARC, a Ca2+‐binding glycoprotein, which exhibits increased level of expression in hypertrophic scars, has been reported to be upregulated by XBP‐1 in hepatocellular carcinoma cells." (PMID 35435317, 2022). "In contrast to SPARC, GRP78, which is often upregulated on the cell surface in malignancy, can interact with PI3K, CRIPTO, IGF1-R in the breast, prostate, and hepatoma cells, respectively, to promote oncogenic events." (PMID 31243264, 2019). "We thus identified SPARC, PLG, G6PC, NR1D2 and AGRP as RORα targets in hepatoma cells." (PMID 21818335, 2011).